LEP (leptin)
Diseases named in the same sentence as LEP in open-access papers (continued):
Sharing a sentence is not in itself a finding about the gene and the disease.
prediabetes (continued). "Consistent with our hypothesis and in line with the extant literature, patients with T2DM and prediabetes experienced higher WC, higher leptin level and worse cardiovascular autonomic function." (PMID 33076921, 2020). "The results of the statistical analysis of leptin levels in obese men with prediabetes showed that the effect of time, the effect of condition (intervention conditions) and the interaction between time and group all significantly affected leptin levels (p < 0.001)." (PMID 41208056, 2025). "However, a study of patients with T2DM and prediabetes patients reported that the CV intake for 12 months decreased plasma leptin levels, while another study reported decreases in leptin levels in obese mice treated with Parachlorella beijerinckii, an algae that is also used as a food supplement." (PMID 39036605, 2024). "Besides, metformin therapy for prediabetes may improve outcomes by a reduction of inflammatory tone and leptin to adiponectin rate in peri-coronary fat in AMI patients." (PMID 32316910, 2020). "In addition, we demonstrated that plasma visfatin and adiponectin levels but not plasma leptin and resistin levels are closely associated with the development of colonic polyps in prediabetes subjects." (PMID 32393372, 2020). "Physical activity promotion with dietary and lifestyle modification may reduce the level of leptin and interleukin-6, but we are uncertain if there is any effect on levels of adiponectin, C-reactive protein, and tumour necrosis factor-α in the individuals with prediabetes." (PMID 38068801, 2023). "This review suggests that physical activity promotion with dietary and lifestyle modification may reduce the level of leptin and interleukin-6 but are uncertain if there is any effect on levels of adiponectin, C-reactive protein and tumour necrosis factor-α in the individuals with prediabetes." (PMID 33211181, 2021). "This review suggests that the physical activity promotion program may reduce the level of leptin and IL-6, but whether there is any effect on the level of adiponectin, CRP, and TNF-α in individuals with prediabetes is uncertain." (PMID 38068801, 2023). "This review suggests that physical activity promotion programme may reduce the level of leptin and IL-6, but it is uncertain whether there is any effect on the level of adiponectin, CRP and TNF-α in individuals with prediabetes." (PMID 33211181, 2021). "However, probiotic or synbiotic administration did not alter leptin or adiponectin levels in individuals with prediabetes and T2DM." (PMID 36239789, 2023). "There was also no statistical difference in fasting leptin or PYY between NGT and prediabetes phenotypes, nor was there an effect on post-prandial PYY iAUC responses during the OGTT." (PMID 41515274, 2026). "Although neither of the two antidiabetic drugs used as prediabetes treatment, metformin and liraglutide, were able to reverse HFHSD-induced DM2, metformin was the superior intervention over liraglutide due to improved central leptin sensitivity and peripheral insulin sensitivity in females." (PMID 37929025, 2023).
intrauterine growth restriction (39 papers, 2011 to 2026). "Intrauterine growth restriction (IUGR) was also associated with decreased leptin levels in both maternal and fetal blood." (PMID 33321877, 2020). "Leptin resistance is associated with lower reproductive efficiency, with deficiencies in embryo viability and growth leading to low prolificacy and high incidence of intrauterine growth restriction." (PMID 30288483, 2018). "Accordingly, leptin levels in umbilical cord at term correlate positively with birthweight and neonatal adiposity and are low in children with intrauterine growth restriction." (PMID 37764824, 2023). "The maternal plasma leptin levels of mothers delivered preterm (75.6 ng/mL) and intrauterine growth-restricted (IUGR) newborns (71.8 ng/mL) were significantly higher than for mothers who delivered at term (44.5 ng/mL)." (PMID 37764842, 2023). "Lower Leptin levels have previously been linked to adverse birth outcomes, including PTB, miscarriage, and intrauterine growth restriction." (PMID 31574087, 2019). "In the present study, we found an important interaction effect of treatment with LPS and leptin and intrauterine growth restriction (and consequently low birth weight) on cytokine secretion." (PMID 30116155, 2018). "The aim of this study was to investigate the relationship between levels of leptin in the cord, and serum leptin of mothers also abnormal color Doppler indices of umbilical artery with fetal growth restriction." (PMID 28580445, 2017). "In the present study, we found that antenatal treatment with leptin for 2 d significantly enhanced the relative alveolus area and improved the maturity of fetal lungs in a rat model of fetal growth restriction (FGR)." (PMID 23894445, 2013). "In previous studies, elevated circulating leptin levels have been found in mothers with fetal growth restriction." (PMID 21906313, 2011). "The most investigated adipokine was maternal serum leptin with 13 studies (one study involved two separate study groups that were taken into consideration individually) and a total of 1081 patients reporting its association with intrauterine growth restriction (IUGR)." (PMID 38541892, 2024). "Maternal blood leptin emerged as the adipokine most investigated, as evidenced by 13 studies encompassing a collective sample size of 1081 patients, all of which explored its potential correlation with intrauterine growth restriction." (PMID 38541892, 2024). "Maternal concentrations of IGF-1, leptin, and insulin are also related to fetal growth, being lower in fetal growth restriction and, conversely, higher in fetal overgrowth, contrary to what happens with adiponectin, which is increased in IUGR and decreased in overgrowth." (PMID 37174902, 2023). "Interestingly, the rat offspring of intrauterine growth restriction also demonstrated leptin resistance, indicated by suppressed leptin-induced STAT phosphorylation." (PMID 21637839, 2011). "On the other hand, intrauterine growth restriction (IUGR) may also lead to leptin resistance." (PMID 29212463, 2017). "It was shown that the babies with intrauterine growth retardation showed relatively increased GH and low IGF-1 and IGFBP-3 concentrations, relatively low leptin, and increased ghrelin values." (PMID 24228030, 2013). "In addition, the protein expression of leptin, VEGFA, IL-6 was increased and negatively correlated to mTORC2 signaling in human placentas collected from pregnancies complicated by intrauterine growth restriction (IUGR)." (PMID 34805133, 2021).
thyroid cancer (39 papers, 2011 to 2025). "Studies also revealed lower APN in patients with thyroid cancer, whereas higher levels of IL-6 and leptin were associated with more advanced papillary thyroid cancer (PTC)." (PMID 37374075, 2023). "Although there is a possibility of an association between leptin level and weight change in thyroid cancer participants, this remains to be further studied." (PMID 35682332, 2022). "Overexpression of leptin and its receptors is significantly associated with the aggressiveness of thyroid cancer." (PMID 33194342, 2020). "In summary, our meta-analysis suggests that adipokines, including TNF-α, IL-6 and leptin are associated with thyroid carcinoma." (PMID 32819324, 2020). "The cause and effect relationship between leptin and thyroid carcinoma are unclear now and need further studies." (PMID 32819324, 2020). "The ratio of leptin immunoreactivity in tissues is significantly associated with the risk of thyroid carcinoma (OR = 12.21, 95% CI: 3.36 to 44.40, I2 = 85%, P < 0.00001)." (PMID 32819324, 2020). "Leptin promoted thyroid cancer progression is associated with the Janus kinase 2 (JAK)-signaling transducer and activator of transcription (STAT)-3 signaling pathway and with STAT3 target gene expression." (PMID 27050378, 2016). "Given that elevated serum leptin levels are observed in obese patients, this adipokine may be associated with the onset and progression of thyroid cancer." (PMID 40620232, 2025). "It is also been reported that circulating leptin levels are also associated with thyroid carcinoma." (PMID 33587254, 2021). "Insulin-like factors and leptin have been suggested to play vital roles in thyroid carcinoma growth, and they have been associated with the aggressiveness of PTC in obese patients by increasing insulin or insulin-like growth factor levels through the PI3K/AKT and JAK2-STAT3 signaling pathways." (PMID 29085428, 2017). "Therefore, association of leptin level with thyroid cancer has been suggested recently." (PMID 22007338, 2011). "An in vitro study revealed that leptin activates the PI3K pathway and promotes the phosphorylation of AKT, thereby triggering critical pathways linked to the proliferation of thyroid cancer cells." (PMID 40620232, 2025). "Increased leptin secretion in the obese state activates various signaling pathways to modulate the growth and proliferation of thyroid carcinoma cells." (PMID 40535346, 2025). "Further, leptin can enhance the migration of thyroid cancer cells through the PI3K/AKT and MEK/ERK signaling pathways." (PMID 38800384, 2024). "Both leptin and its receptor are highly expressed in thyroid cancer, salivary gland carcinoma, oral squamous cell carcinoma, and laryngeal cancer." (PMID 38800384, 2024). "Overexpression of leptin and its receptor (OB-R) has been found in many cancers, including thyroid carcinomas." (PMID 35162142, 2022). "Overall, data in the literature suggest that elevated serum and tissue leptin concentrations correlate with thyroid carcinomas, and that leptin promotes neovascularization in tumor tissue and induces VEGF expression." (PMID 35162142, 2022). "Invasion ability of thyroid cancer cells in response to Acrp30 or leptin treatment, alone, or in combination was analyzed by Matrigel Matrix invasion assay." (PMID 33587254, 2021). "Consequently, even if the prognostic value of Acrp30, leptin, and their receptors remain controversial and further research are needed, our data underline the importance of monitoring the levels of these adipokines and their receptors in thyroid cancer patients." (PMID 33587254, 2021). "In humans, recombinant TSH administered to patients with differentiated thyroid cancer during postoperative diagnosis stimulated leptin secretion." (PMID 34574358, 2021). "In vitro studies have indicated that leptin promotes invasion and migration of thyroid cancer cell lines." (PMID 35004287, 2021).
thyroid cancer (continued). "Altogether, these data encourage deepening the research role of Acrp30 and leptin in TC as useful therapeutic targets and biomarkers for thyroid cancer." (PMID 33587254, 2021). "In this study, we first analyzed the expression levels and prognostic values of Acrp30, leptin, and their receptors in thyroid cancer cells." (PMID 33587254, 2021). "q-RT-PCR showed that the vast majority of the thyroid cancer cell lines tested, although with heterogeneity, expressed leptin and Acrp30 (AdipoR1, AdipoR2, and T-Cadherin) receptors when compared to Nthy-ori 3-1." (PMID 33587254, 2021). "In this scenario, we have evaluated in vitro effects of Acrp30 and leptin in thyroid cancer cell lines." (PMID 33587254, 2021). "They found that leptin increased the migration of PTC cells but inhibited this ability in anaplastic and follicular cancer cells suggesting that leptin modulates cell migration of thyroid cancer cells in a cell type-specific manner." (PMID 33587254, 2021). "Leptin is always reported a high expression on solid tumors, and it is confirmed that serum leptin level is significantly increased in thyroid cancer (mainly PTC), while other studies showed a same results in cancer tissues." (PMID 32819324, 2020). "Previously, we demonstrated that leptin and adiponectin receptors were expressed in a subset of thyroid cancer and provided prognostic information in addition to clinical characteristics." (PMID 32111875, 2020). "Adipokines (TNF-α, IL-6 and leptin) show a strong relationship between elevated concentrations (in serum and/or tissue) and thyroid carcinoma." (PMID 32819324, 2020). "The search for novel molecular targets in aggressive DTCs unresponsive to current treatments and recent reports on the role of leptin and OB-R in some malignancies prompted us to investigate the possibility of targeting OB-Rs in thyroid cancer." (PMID 30906321, 2019). "Different thyroid cancer cells were treated with 20 μM OB3 or 50 ng/mL leptin for 144 hours with media and reagents refreshed daily." (PMID 27050378, 2016). "Similar studies were conducted with leptin to compare proliferative effects of OB3 and leptin in thyroid cancer cells." (PMID 27050378, 2016). "Results indicated that there was no significant change among proliferation in control, OB3- or leptin-treated cancer cells in 5 different types of thyroid cancer cells." (PMID 27050378, 2016). "In the present study, we compared the signal transduction and other known mechanisms of action of leptin peptide with OB3 peptide actions in thyroid cancer cells." (PMID 27050378, 2016). "In the present study, because of a close link between leptin and the hypothalamic-pituitary-thyroid axis, OB3 was compared with leptin in different thyroid cancer cells for gene expression, proliferation and invasion." (PMID 27050378, 2016). "Clinical studies have shown that there is a strong correlation of the leptin expression with the Ob-R expression in thyroid cancer cells." (PMID 27050378, 2016). "Thyroid cancer cells were treated with different concentrations of leptin for 144 hours with re-freshed leptin daily." (PMID 27050378, 2016). "In summary, OB3 is a derivative of leptin that importantly lacks the mitogenic effects of leptin on thyroid cancer cells." (PMID 27050378, 2016). "We next examined expression of proliferative genes induced by OB3 and leptin in thyroid cancer cells." (PMID 27050378, 2016). "It is also suggested that leptin and its receptors have a role in the pathogenesis of thyroid cancer." (PMID 24049662, 2013). "Serum leptin levels in thyroid cancer group were significantly higher than control group (P < 0.05)." (PMID 22007338, 2011). "Considering that thyroid cancer is the most common endocrine cancer, the aim of this study was evaluation of leptin levels in thyroid cancer." (PMID 22007338, 2011).
thyroid cancer (continued). "In conclusion, numerous studies have elucidated the role of leptin in thyroid cancer, demonstrating its capacity to enhance cell growth and survival through mechanisms that include the promotion of cell proliferation, the reduction of apoptosis, and the regulation of metabolic activity." (PMID 40620232, 2025). "Fan and Li found a strong correlation between leptin and the aggressiveness of thyroid cancer." (PMID 36389127, 2022). "Interestingly, K1 and BCPAP cells co-treated with Acrp30 and leptin displayed the same invasion capability of untreated cells indicating that Acrp30 and leptin display antagonizing effects on thyroid cancer cell invasion." (PMID 33587254, 2021). "Additionally, through wound healing and Matrigel Matrix invasion assays, we unveiled that Acrp30 inhibits thyroid cancer cell motility, while leptin induces the opposite effect." (PMID 33587254, 2021). "Finally, we investigated the prognostic value of Acrp30, of leptin, and of their receptors in thyroid cancer patients consulting the TCGA-THCA." (PMID 33587254, 2021). "Highlights of these studies suggest that Acrp30 and leptin could represent therapeutic targets and biomarkers for the management of thyroid cancer." (PMID 33587254, 2021). "Due to the absence of direct evidence, elevated leptin levels can also be caused by thyroid carcinoma." (PMID 32819324, 2020). "In thyroid cancer, there are few studies regarding the relationship between leptin and the EMT process, but some reports have demonstrated that treatment with leptin can promote cell growth and modulated migration of CCs, as well as inhibiting apoptosis through of the upregulation of the XIAP gene." (PMID 31109060, 2019). "In this translational study, we analyzed in vitro the effects of leptin on the growth and migration of thyroid cancer cells (TPC-1 and K1), the molecular mechanisms underlying leptin's action, and the influence of prolonged leptin exposure on cell response to a protein kinase inhibitor lenvatinib." (PMID 30906321, 2019). "Two factors in our study support the relationship between leptin and thyroid cancer." (PMID 24867470, 2014). "Since it is reported in literature that the leptin effects are mediated by MAPK signaling pathway in thyroid cancer, here we evaluated whether the pharmacological inhibition of BRAF impairs the combined effects of the two adipokines on thyroid cancer cell proliferation." (PMID 33587254, 2021). "Additionally, since leptin is known to exhibit opposite Acrp30 actions, we evaluated the combined effect of these adipokines on malignant hallmarks of PTC transformation, and we found that Acrp30 and leptin have antagonizing effects on thyroid cancer cell proliferation and motility." (PMID 33587254, 2021). "Thus, leptin may be involved in the tumorigenesis and metastasis of thyroid cancer through a complex pathway and a monitoring may have some significance." (PMID 32819324, 2020). "Thus, leptin has thyroid cancer-type-specific actions on gene transcription." (PMID 32645835, 2020). "Moreover, the pooled OR of the ratio of leptin immunoreactivity in tissues from five studies is 12.21 (95%CI 3.36 to 44.40), which means a high ratio of leptin immunoreactivity in tissue is significantly related to thyroid carcinoma." (PMID 32819324, 2020). "However, it cannot be excluded that a complete inhibition of leptin-induced effects on thyroid cancer cells may increase the effects of PKIs and thus decrease the dosage needed to be effective." (PMID 30906321, 2019). "Leptin may play a role in the development of thyroid cancers." (PMID 27050378, 2016). "Leptin acting via leptin receptor may regulate cell migration of thyroid cancer cells." (PMID 27050378, 2016). "So leptin also may have role in pathogenesis and prognosis of thyroid cancers." (PMID 24049662, 2013). "Leptin can increase the expression of VEGF, interleukin-6 (IL-6), and tumor necrosis factor-α (TNF-α) to promote progression and metastasis of thyroid cancer." (PMID 33194342, 2020).